ATP1A3 (ATPase Na+/K+ transporting subunit alpha 3)
Diseases named in the same sentence as ATP1A3 in open-access papers (continued):
Sharing a sentence is not in itself a finding about the gene and the disease.
cone-rod dystrophy (1 paper, 2022). Inherited retinal dystrophies that belong to the group of pigmentary retinopathies. "A recent whole-exome sequencing study reported that high expression of an ATP1A3 mutation led to cone-rod dystrophy through limiting mitochondrial reserve capacity." (PMID 35153787, 2022).
diabetic kidney disease (1 paper, 2025). Progressive kidney disorder caused by vascular damage to the glomerular capillaries, in patients with diabetes mellitus. "In the human Diabetic Kidney Disease (DKD) tissues, Atp1a3, and Ncf1 were mainly expressed in leukocytes, with their expression levels elevated in the DKD group." (PMID 40305204, 2025).
gastric cancer (1 paper, 2023). A primary or metastatic malignant neoplasm involving the stomach. "In contrast, overexpressed ATP1A3, which promotes tumor invasion, has been identified in clinical specimens of gastric cancer." (PMID 38022687, 2023).
hereditary generalized epilepsy (1 paper, 2022). An instance of generalized epilepsy that is caused by an inherited genomic modification in an individual. "In addition, a study found that among the common mutations in the ATP1A3, rs8107107 is associated with hereditary generalized epilepsy, especially with generalized tonic–clonic seizures." (PMID 35968298, 2022).
Hydrocephalus (1 paper, 2019). Hydrocephalus is an active distension of the ventricular system of the brain resulting from inadequate passage of CSF from its point of production within the cerebral ventricles to its point of absorption into the systemic circulation. "Consistent with our results, morpholino knockdown of Atp1a3 causes ventriculomegaly in zebrafish, recapitulating the hydrocephalus phenotype in our patient." (PMID 31616254, 2019). "Knockdown of Atp1a3 in zebrafish results in hydrocephalus; however, no known association exists between ATP1A3 and human CH." (PMID 31616254, 2019).
infantile-onset epilepsy (1 paper, 2019). Epilepsy starting in the first 12 months of life, including self-limiting and refractory seizures, and epilepsies with and without developmental disorders. "Additional infantile-onset epilepsy patients linked with ATP1A2 and ATP1A3 are found in the literature." (PMID 31572294, 2019).
insomnia (1 paper, 2023). A sleep disorder characterized by difficulty in falling asleep and/or remaining asleep. "A very high prevalence of insomnia was recently reported in patients with childhood alternating hemiplegia, some of which harboured mutations in Atp1a3, consistent with our observations that insomnia at night is a direct behavioural consequence of atp1a3a mutation in zebrafish." (PMID 37548652, 2023).
Jeavons syndrome (1 paper, 2025). "ATP1A3, a member of the sodium-potassium ATPase gene family, has also been implicated in the pathogenesis of Jeavons syndrome." (PMID 40969926, 2025).
left ventricular hypertrophy (1 paper, 2020). Enlargement of the LEFT VENTRICLE of the heart. "Only 1 patient with AHC carrying the ATP1A3 mutation c.2839G>C-G947R, who was 46 years of age, had left ventricular hypertrophy." (PMID 32913013, 2020).
Machado-Joseph disease (1 paper, 2024). "The most common polyQ SCA were Machado-Joseph disease (MJD/SCA3) (73.7%) and SCA2 (15.8%); whereas in non-repeat expansion SCA ATX-CACNA1A (14.3%), ATP1A3-related ataxia, ATX-ITPR1, ATX/HSP-KCNA2, and ATX-PRKCG (9.5% each) predominated." (PMID 39048885, 2024).
myopia (1 paper, 2022). "Further research is needed to characterize the relationship between ATP1A3 protein expression and myopia." (PMID 35153787, 2022). "Although abnormal mitochondrial function has been reported during myopia progression, ATP1A3 had not been previously implicated." (PMID 35153787, 2022). "Therefore, it may be speculated that up-regulation of ATP1A3 (FDM + A4 vs FDM) may retard myopia by maintaining normal mitochondrial function after atropine treatment." (PMID 35153787, 2022).
Nystagmus (1 paper, 2022). Rhythmic, involuntary oscillations of one or both eyes related to abnormality in fixation, conjugate gaze, or vestibular mechanisms.
prion disease (1 paper, 2025). A transmissible disease that is caused by a protein that is able to induce abnormal folding of normal cellular proteins, leading to characteristic spongiform brain changes, which are associated with neuronal loss without an inflammatory response. "Apart from ATP1A3 and prion disease, rapid onset or progression is not expected." (PMID 40118803, 2025).
respiratory arrest (1 paper, 2020). "A female patient with AHC (c.410C>T; p.S137F mutation in ATP1A3) started experiencing episodes of loss of consciousness with respiratory arrest at 21 years of age10 Her routine 12-lead ECG was normal." (PMID 32913013, 2020).
retinoblastoma (1 paper, 2022). A malignant tumor that originates in the nuclear layer of the retina. "To investigate whether retinoschisin affects the potassium ion currents mediated by the Kv channels, we performed patch-clamp analyses using the retinal human retinoblastoma cell line Y-79, endogenously expressing Kv2.1, Kv8.2, ATP1A3, and ATP1B2, but not retinoschisin." (PMID 35876901, 2022).
Snijders Blok-Campeau syndrome (1 paper, 2025). Snijders Blok-Campeau syndrome (SNIBCPS) is an autosomal dominant neurodevelopmental disorder characterized by global developmental delay with impaired intellectual development and delayed speech acquisition. "A patient with an ATP1A3 mutation (Snijders Blok-Campeau syndrome) exhibited frontal bossing and a round face." (PMID 41300846, 2025).
stenosis (1 paper, 2019). "Together, these data provide evidence for a recessive inheritance of CH with aqueductal stenosis caused by ATP1A3 compound heterozygous mutations." (PMID 31616254, 2019).
vascular dementia (1 paper, 2023). A degenerative vascular disorder affecting the brain. "ATP1A3 was previously identified as one potential marker for AD diagnosis compared with vascular dementia." (PMID 37762226, 2023).
Ventriculomegaly (1 paper, 2019). An increase in size of the ventricular system of the brain. "Our findings suggest two separate but not necessarily mutually exclusive mechanisms whereby ATP1A3 compound heterozygous mutations may cause ventriculomegaly." (PMID 31616254, 2019).
X-linked juvenile retinoschisis (1 paper, 2014). "The recent demonstration that the Na+/K+-ATPase α3 subunit plays a critical role in anchoring retinoschisin, the protein involved in X-linked juvenile retinoschisis, to photoreceptor and bipolar cells of the retina in a mouse model is compatible with involvement of ATP1A3 in visual function." (PMID 24468074, 2014).
neurological disorders (39 papers, 2013 to 2026). "Although Atp1a3 has been extensively characterized for its predominant distribution in the neural system and its association with various neurological disorders, its role in BAT and metabolic regulation remains largely uncharacterized." (PMID 41019552, 2025). "In particular, mutations of atp1a3 in human patients were implicated in multiple neurological disorders involving abnormal movements, altered awareness, and autonomic dysfunction." (PMID 39453165, 2024). "Single-cell exploration has pointed toward a critical role for ATP1A3 in human brain development and a cell type basis for ATP1A3-associated neurological disorders." (PMID 36866063, 2023). "Multiple studies have already shown the causal significance of ATP1A3 polymorphisms in developing various neurological diseases with a common inheritance mode." (PMID 36866063, 2023). "Despite physiological conditions, substantial evidence has suggested that pathogenic variants in ATP1A3 are potential causes of various neurological disorders." (PMID 36866063, 2023). "It has now been established that protein-modifying genetic variations in ATP1A3 are uncommon in the general population and that when they do exist, they carry a very high risk of causing severe neurological disorders." (PMID 36866063, 2023). "We describe the phenotypic features of individuals carrying a pathogenic/likely pathogenic ATP1A3 variant and perform a literature review of all ATP1A3 variants published thus far in association with human neurologic disease." (PMID 36192182, 2022). "We also perform a literature review of all ATP1A3 variants published thus far in association with human neurologic disease." (PMID 36192182, 2022). "The link between heterozygous missense mutations in the ATP1A3 gene and the manifestation of rare neurological disorders was first established in 2004." (PMID 34612482, 2021). "Sporadic or inherited mutations in ATP1A2 and ATP1A3 have been identified and associated with various neurologic disorders." (PMID 33544780, 2021). "Genetic mutations in the ATP1A2 gene and ATP1A3 gene, encoding the α2 and α3 subunit isoforms, respectively can cause distinct neurological disorders, concurrent to impaired NKA activity." (PMID 27313535, 2016). "Deficient function of the α2- or α3-isoform of the Na+/K+-ATPase, caused by mutations in the genes ATP1A2 or ATP1A3, is associated with the neurological diseases hemiplegic migraine (HM) and rapid-onset dystonia parkinsonism (RDP), respectively." (PMID 24236096, 2013). "The results of the present study provide a sound basis for employing the ATP1A3 promoter in attempts to generate transgenic porcine models of neurological diseases caused by ATP1A3 mutations." (PMID 24236096, 2013). "Pathogenic variants of ATP1A3 are linked to various groups of neurological disorders." (PMID 39839618, 2024). "Mutations in the ATP1A3 gene mutation cause a broad spectrum of neurologic disorders." (PMID 37008993, 2023). "Drugs that control monoamine signaling may be effective in treating ATP1A3 mutation-related neurological diseases, where it has been hypothesized that high monoamine levels are a consequence of seizure activity rather than a cause." (PMID 36866063, 2023). "The presented results might help guide the diagnosis and treatment of ATP1A3-related diseases and provided new ideas for further exploring the mechanisms of nervous system diseases due to ATP1A3 mutations." (PMID 35968298, 2022). "We propose that decreases in ASC levels may affect neural network development and are linked to the pathophysiology of ATP1A2- and ATP1A3-related neurologic disorders." (PMID 33544780, 2021). "Interestingly, the complexity of ATP1A3-related disorders is emphasized by the fact that clinically distinct neurological diseases seem to be caused by mutations in a single gene." (PMID 27549929, 2016).
neurological disorders (continued). "Therefore, our research may provide new insights into the in-depth exploration of the potential pathogenic mechanisms of ATP1A3-related neurologic disorders." (PMID 39145297, 2024). "Dominant ATP1A3 mutations may cause a broad spectrum of neurological diseases." (PMID 36866063, 2023). "The ATP1A3 gene, which encodes the Na+/K+-ATPase α3 catalytic subunit, plays a crucial role in both physiological and pathological conditions in the brain, and mutations in this gene have been associated with a wide variety of neurological diseases by impacting the whole infant development stages." (PMID 36866063, 2023). "Among ATP1A3-related neurologic disorders, RDP is characterized by sudden attacks of primarily bradykinesia and postural instability, often accompanied by marked medullary symptoms." (PMID 39145297, 2024). "ATP1A3-related neurologic disorders are rare, but over the past decade, they have garnered increased attention." (PMID 39145297, 2024). "It is very similar to ATP1A3 mutations-mediated AHC because missense mutations into only some specific regions of ATP1A3 cause AHC and the other mutations cause different neurological diseases with similar symptoms except for hemiplegia." (PMID 36978081, 2023). "The onset of symptoms of ATP1A3-related neurologic disorders is almost always related to physical and psychological stress." (PMID 33544780, 2021). "ATP1A3-related neurologic disorders often manifest due to physical and/or psychological triggers, including childbirth." (PMID 33544780, 2021). "This clinical spectrum of disease is now summarized as ATP1A3-related neurological disorder, and our patient’s phenotype belongs to mixed phenotype of RDP and AHC." (PMID 32963807, 2020). "Atp1a3 mouse models have provided insights into the role of the α3 isoform in neurological diseases." (PMID 27549929, 2016). "Although the ATP1A3-related neurological disorders are considered clinically distinct, the phenotypic spectrum of each disease continues to expand." (PMID 27378932, 2016). "ATP1A3 was previously shown to be mutated in Rapid-Onset Dystonia-Parkinsonism (RDP, DYT12, MIM#128235), a rare neurological disorder characterized by abrupt onset of dystonia and triggered by emotional or physical stress." (PMID 25996915, 2015). "This study provides a proof-of-concept for in vivo prime editing to rescue a neurological disorder, and our data suggest that therapeutic ATP1A3 PE could address the urgent unmet clinical need in AHC." (PMID 40695277, 2025). "The analysis of the ATP1A3 genotype–phenotype relationship might help guide the diagnosis and management of nervous system diseases." (PMID 35968298, 2022). "Therefore, further analysis of the clinical characteristics of ATP1A3 and the genotype–phenotype relationship helped in the clinical diagnosis and treatment of neurological diseases." (PMID 35968298, 2022). "The currently identified clinical phenotypes of neurological disorders associated with ATP1A3 mutations were overlapping but not completely consistent." (PMID 35968298, 2022). "Owing to this heterogeneity of symptomatic manifestations, sometimes even within the same family, ATP1A3-related neurologic disorders are now considered a clinical continuum and have a wide range of severity, age of onset, and progression of different signs and symptoms." (PMID 33544780, 2021). "Notably, the onset of symptoms in ATP1A2- and ATP1A3-related neurologic disorders is usually triggered by physiological or psychological stressors." (PMID 33544780, 2021). "ATP1A3-related syndromes are cardiac diseases and neurologic diseases." (PMID 32913013, 2020). "However, severe neurological disorders have been associated with variants in the ATP1A2 and ATP1A3 genes encoding the α2 and α3 subunit isoforms." (PMID 28620085, 2017). "Therefore, it is likely that decreased levels of ASC may contribute to the symptomatic manifestation of ATP1A2/ATP1A3-related neurologic disorders." (PMID 33544780, 2021).
neurological disorders (continued). "Not surprisingly, mutations in the ATP1A3 gene have been associated with neurological disorders." (PMID 27378932, 2016).
movement disorder (9 papers, 2014 to 2025). Neurological conditions resulting in abnormal voluntary or involuntary movement, which may impact the speed, fluency, quality and ease of movement. "Here, we report two novel variants in ATP1A3 (NM_152296.5) found in patients with movement disorders." (PMID 35181663, 2022). "In this study, we performed whole exome sequencing for two patients with movement disorders and identified two novel heterozygous ATP1A3 variants, a missense c.2408G>A variant and an indel c.2672_2688+10delinsCAG variant." (PMID 35181663, 2022). "Variants in ATP1A3 cause neuropsychiatric disorders, especially those characterized by movement disorders." (PMID 35181663, 2022). "With some exceptions (e.g., ADCY5-, KMT2B-, ATP1A3-related movement disorders), the number of reported patients affected by these novel genetic entities is still rather limited." (PMID 29086067, 2017).
tumor (8 papers, 2018 to 2025). "Multivariate analysis showed that primary therapy outcome (p < 0.001), residual tumor (p = 0.001), ATP1A3 (p = 0.006), and ATP1A4 (p = 0.017) were independent risk factors for DSS." (PMID 32684846, 2020). "RNA sequencing results revealed significant differences in gene expression, with key genes (upregulated CXCR4, OPCML, and S100A2, and downregulated ATP1A3, CHL1, HLA-DRA, and IL-1β) associated with tumor invasiveness." (PMID 41374320, 2025). "Univariate analysis identified primary therapy outcome (p < 0.001), residual tumor (p < 0.001), ATP1A3 (p = 0.002), and ATP1A4 (p = 0.023) as prognostic factors for DSS." (PMID 32684846, 2020). "Multivariate analysis showed that primary therapy outcome (p < 0.001), residual tumor (p = 0.004), ATP1A2 (p = 0.006), ATP1A3 (p < 0.001), and ATP1A4 (p < 0.001) were independent risk factors for OS." (PMID 32684846, 2020). "First, when comparing the differential expression of ATP1A2 and ATP1A3 in tumor and normal tissues, it was found that the results from the TCGA and ICGC databases were contradictory." (PMID 32684846, 2020). "Multivariate analysis showed that primary therapy outcome, residual tumor, and mRNA expressions of ATP1A3 and ATP1A4 were independent prognostic factors for both OS and DSS in patients with OSC." (PMID 32684846, 2020). "ATP1A1 and ATP1A3 were highly expressed in tumor tissues, whereas ATP1A2 and ATP1A4 were highly expressed in normal tissues (all p < 0.001)." (PMID 32684846, 2020). "Univariate analysis identified primary therapy outcome (p < 0.001), age (p = 0.032), residual tumor (p < 0.001), ATP1A3 (p < 0.001), and ATP1A4 (p = 0.03) as prognostic factors for OS." (PMID 32684846, 2020). "Furthermore, we identified that primary therapy outcome, residual tumor, ATP1A3 gene, and ATP1A4 gene were independent indicators of OS and DSS in OSC." (PMID 32684846, 2020). "Moreover, primary tumor outcome, residual tumor, ATP1A2, ATP1A3, and ATP1A4 were closely related to the risk of recurrence and mortality in OSC." (PMID 32684846, 2020). "We observed low expression of ATP1A3 and its correlation with increased KRAS signaling and other oncogenic pathways aligns with evidence showing the importance of Na+/K+-ATPase in tumor progression." (PMID 41374320, 2025). "The expression of ATP1A3 and GNB3 in tumor tissues was significantly higher than that in normal tissues." (PMID 36237326, 2022). "Based on the results of multivariate analysis, a genomic-clinical nomogram, including primary tumor therapy outcome, residual tumor, ATP1A2, ATP1A3, and ATP1A4, was established to predict the 1-, 3-, and 5-year OS and DSS in patients with OC." (PMID 32684846, 2020). "For some antigens like ATP1A3, ITPR1, or ROCK2 an expression in tumor samples of the respective index patient was observed, pointing to a paraneoplastic autoimmune background." (PMID 30038610, 2018).